RUNX1 (RUNX family transcription factor 1)
Diseases named in the same sentence as RUNX1 in open-access papers (continued):
Sharing a sentence is not in itself a finding about the gene and the disease.
leukemia (continued). "In leukemia cells, studies have found a corresponding regulatory relationship between RUNX1 and BCL2, in which BCL2 as an essential regulator participates in the dual function of RUNX1 on survival." (PMID 37760803, 2023). "RUNX1 is involved in embryogenesis, leukaemia, vascularization, immune response and tumour formation." (PMID 36541023, 2023). "Given that RUNX1/ETO is leukaemia-specific, it would serve an ideal target for RNA interference (RNAi)-based therapies." (PMID 36823395, 2023). "Here, we characterize the ETV6-RUNX1 chimeric- and native RUNX1-responsive regulomes and explore their relationship in the context of pre-leukemia and overt disease." (PMID 36411286, 2022). "The functional antagonism between the two transcription factors exposes an addiction to RUNX1-activity in overt leukemia, spanning pediatric and adult B-ALL subtypes." (PMID 36411286, 2022). "The UBASH3A, SF3B1, RUNX1 and ASXL1 mutations gradually appeared and became the major clones at MDS stage, while IDH2 gradually emerged as the dominant clone at leukemia stage." (PMID 36167633, 2022). "The NF-kB inhibitor BMS-345541 inhibits the proliferation of leukemia cells containing RUNX1 mutation, suggesting a potential role of NF-κb inhibitors in targeting RUNX1-related leukemia." (PMID 35399522, 2022). "The clonal evolution analysis of FA case (P1001) showed the mutations of UBASH3A, SF3B1, RUNX1 and ASXL1 gradually appeared at the later stage of MDS, while the IDH2 alteration become the dominant clone at the leukemia stage." (PMID 36167633, 2022). "subsequently identified a splice variant which generates a 575 amino acid protein, termed RUNX1-RUNX1T19a, that is variably expressed in human AML and generates leukemia when transduced into murine fetal liver cells." (PMID 35756660, 2022). "In accordance with the findings, knocking down RUNX1 inhibited leukaemia cells growth in both human CD34+ cells transduced with MLL‐AF9 and the MLL‐AF9 mouse model." (PMID 36467848, 2022). "All mice transplanted with RUNX1-RUNX1T19a expressing cells developed leukemia within 16 weeks of transplant." (PMID 35756660, 2022). "Genes associated with the “R1_ER” peaks were enriched in GO-terms relating to the cell cycle suggesting that the cell cycle phenotype we observe in our pre-leukemia model results from competition between RUNX1 and the fusion." (PMID 36411286, 2022). "Evidence from animal studies indicates that RUNX1 overexpression in mice shortens the latency of leukemia development displaying enhanced frequency of megakaryoblastic leukemia, which supports that RUNX1 overexpression is leukemogenic in ML-DS." (PMID 36035173, 2022). "In frank leukemia, knockdown of RUNX1 or its co-factor CBFβ results in cell death suggesting sustained requirement for RUNX1 activity which is recapitulated by chemical perturbation using an allosteric CBFβ-inhibitor." (PMID 36411286, 2022). "Most of the RUNX1 mutations are mono-allelic, such as in FPD, an IBMFS resulting in a predisposition to leukemia." (PMID 35765406, 2022). "To functionally assess the requirement for RUNX1 in leukemia, we depleted RUNX1 in vitro in four B-ALL cell lines and a control chronic myeloid leukemia (CML) cell line and monitored proliferation of leukemic cells over nine days (red asterisks, and 7a)." (PMID 36411286, 2022). "Leukemic cells of core‐binding factor AML and certain types of leukaemia with MLL rearrangements require normal RUNX1 to survive." (PMID 36467848, 2022). "CBFβ Inhibitor has been shown to alter the ability of RUNX1 to bind to target genes and alter their expression, thereby inhibiting the growth of leukemia and breast cancer cell lines." (PMID 35458567, 2022). "The transcription factor RUNX1 is a critical regulator of developmental hematopoiesis and is frequently disrupted in leukemia." (PMID 35140205, 2022). "THP-1 cells exhibit aberrantly high RUNX1 expression and the addition of a RUNX1 inhibitor can greatly reduce leukemia cell number." (PMID 34434964, 2021).
leukemia (continued). "Pan-cancer analysis results showed that RUNX1 increased significantly in 58 datasets, especially those of leukemia, head and neck cancer, colorectal cancer, kidney cancer, and breast cancer." (PMID 34294773, 2021). "Our results indicated that RUNX1 facilitates cell proliferation and provides leukemia cells with a growth advantage." (PMID 34434964, 2021). "RUNX1 S291fs/Ezh2 promotes MDS development by activating inflammatory cytokine responses but attenuates leukemia development via PRC1 mediated repression of Hoxa9." (PMID 34944812, 2021). "Core inding factor (CBF) leukemia subtypes, which includes leukemias harboring fusion genes CBFB/MYH11 or RUNX1/RUNX1T1, are associated with younger age and range from 20% in pediatric to less than 5% in older AML patients." (PMID 34947882, 2021). "To understand the role that dysregulated wild-type RUNX1 plays to promote leukemia development, we needed to identify potential THP-1-specific RUNX1 target genes." (PMID 34434964, 2021). "Runt-related transcription factor 1 (RUNX1) is one of the components of core-binding transcription factors involved in hematopoiesis and leukemia." (PMID 34593006, 2021). "The first molecular evidence for a prenatal origin of childhood leukemia arose from twin studies of KMT2A-rearranged and ETV6/RUNX1 leukemia published in the 1990s." (PMID 33968846, 2021). "Moreover, our data seem to suggest that double RUNX1 mutations are enriched in leukemias with an undifferentiated phenotype and may support the hypothesis that AUL and AML with minimal differentiation represent a continuum of disease with a similar genetic background." (PMID 34540694, 2021). "Nevertheless, RNAi-mediated cohesin knockdown was found to enhance RUNX1 transcription in the leukemia HL60 cell line." (PMID 33928020, 2021). "Overall, our results indicated that RUNX1 promoted leukemia cell growth mainly through up-regulating cell proliferation." (PMID 34434964, 2021). "When TMX was injected at 4 weeks old, eR1-CreERT2 Tg; Rosa26-LSL-RUNX1-ETO-IRES-EGFP; Rosa26-LSL-NrasG12D mice developed leukemia with complete penetrance and shorter latency as compared to RUNX1-ETO alone model." (PMID 34148054, 2021). "We demonstrated that one mechanism by which CBFA2T3 and RUNX1 promote leukemogenesis or maintain leukemia is by controlling cell proliferation." (PMID 33743795, 2021). "WHO criteria allow recognition of this leukaemia entity and its distinction from AML with myelodysplasia-related changes, AML with BCR-ABL1 rearrangement and AML with RUNX1 mutations." (PMID 33879827, 2021). "Point mutations in the 5′UTR of ANKRD26 have shown to result in familial thrombocytopenia 2 and leukemia predisposition, mainly mediated by the derepression of ANKRD26 due to insufficient RUNX1/FLI1 complex binding." (PMID 34502524, 2021). "Overall, our data suggested that RUNX1 can promote leukemia cell growth and maintain the leukemia cell colony-forming ability." (PMID 34434964, 2021). "Runt-related transcription factor 1 (RUNX1; AML1) plays a critical role in the emergence of all definitive hematopoiesis and represents a common mutational target in leukemia." (PMID 34502524, 2021). "Altogether, we demonstrated the existence of a new RUNX1 and CBFA2T3 driver-loop in ETV6-RUNX1 leukemia." (PMID 33743795, 2021). "RUNX1-ETO mRNA amount per one single leukemia cell at clinical onset time is shown to be significantly higher than that at remission state." (PMID 34148054, 2021). "Both fusion partners, RUNX1 and JAK2, are prominent leukemia-associated genes that are often affected by genomic rearrangements or mutations." (PMID 34299194, 2021).
leukemia (continued). "In the present study, we sought to establish an in vitro experimental model to study the intracellular mechanisms of leukemia development downstream of CSF3R and RUNX1 mutations." (PMID 32821971, 2020). "In leukemia cells, Runx1 (Runt-related transcription factor 1) directly interacts with and recruits JMJD1C to target genes." (PMID 32625104, 2020). "Loss of the Y-chromosome in male patients correlated with improved RFS in univariate analysis in RUNX1/RUNX1T1 leukemia (HR = 0.39, p = 0.047)." (PMID 31896782, 2020). "Of note, small molecule drugs inhibiting Runx1 have already passed pre-clinical testing in the context of leukaemia treatment." (PMID 32341028, 2020). "RUNX1/ETO maintains leukemia by promoting cell cycle progression and identifies G1 CCND-CDK complexes as promising therapeutic targets for treatment of RUNX1/ETO-driven AML." (PMID 32231866, 2020). "Patients with SCN reportedly have a 21% cumulative incidence of myeloid malignancy after 10 years with the risk of leukemia being higher in patients requiring high doses of G-CSF, and is associated with acquired mutations in CSF3R and RUNX1." (PMID 32066420, 2020). "In contrast to RUNX1 and RUNX3, whose mutations are closely linked to the promotion of leukemia and GC, respectively, the initial studies suggest that RUNX2 acts as a master regulator of osteoblast differentiation and bone development." (PMID 33313404, 2020). "Located on chromosome 21, the RUNX1 gene is involved in many forms of chromosomal translocations in leukemia." (PMID 32231866, 2020). "An indirect pathway of MYC activation in ETV6/RUNX1-rearranged leukemia is mediated by the GTP-binding protein RAC1, a pivotal modulator of hematopoiesis, that increases the phosphorylation levels of STAT3." (PMID 32102485, 2020). "In summary, our study provides a detailed overview of cooperating mutations in one of the largest adult CBF leukemia cohorts so far and highlights fundamental differences between CBFB/MYH11- and RUNX1/RUNX1T1-rearranged leukemia." (PMID 31896782, 2020). "Expression of RUNX1/ETO in HSPCs blocks differentiation and enhances self-renewal capacity but leukemia develops as a result of concurrent mutations in signaling pathways and tyrosine kinases (class 1 mutations) that affect cell proliferation." (PMID 33322186, 2020). "RUNX1 and CBFB are frequent targets of gene rearrangements through chromosomal translocations and mutations that are associated with human leukemias." (PMID 31817911, 2019). "RUNX1 gene is the master regulator of definitive hematopoiesis in humans; therefore, defective cell differentiation contributes to the onset of leukemia." (PMID 31366376, 2019). "Co-expression of two mutant genes increased myeloid stem cells in animal model, suggesting that cooperation of RUNX1 and ASXL1 mutations played a critical role in leukemia transformation." (PMID 31640815, 2019). "For the induction of leukemia, RUNX1-ETO expression requires additional secondary genetic alterations." (PMID 30654457, 2019). "The expression of IL1RL1 (the gene encoding receptor for IL33), which was reported co-expressed with RUNX1 in mouse and human leukemia cells, was also positively correlated with that of RUNX1." (PMID 31501518, 2019). "In subsequent studies, researchers showed that mice conditionally expressing RUNX1-ETO developed leukaemia only upon treatment with genotoxic agents such as N-ethyl-N-nitrosourea (ENU)." (PMID 30669675, 2019). "Recently, we have shown that leukemia maintenance is dependent on a balance between AML1-ETO, RUNX1, and ERG expression, and that disturbed RUNX1 or ERG function results in AML1-ETO overdose and cell death." (PMID 31869378, 2019). "This is of particular interest as wild type RUNX-1 is essential for the maintenance of MLL-AF9 leukemia." (PMID 31861091, 2019).
leukemia (continued). "Our results demonstrated that RUNX1-MT have critical roles in the leukemia transformation including augmentation of cell proliferation, blocked differentiation, and increased self-renewal activity in ASXL1-mutated cells." (PMID 31640815, 2019). "Based on the lead compound, they found that AI-10-49 selectively binds to CBFβ-SMMHC and disrupts its binding to RUNX1, which thus restores RUNX1 transcriptional activity, displays favorable pharmacokinetics and delays leukemia progression in mice." (PMID 34691990, 2019). "In recent years, increased evidence has emerged about the requirement of RUNX1 in leukemia cells with RUNX1-ETO." (PMID 30654457, 2019). "To further investigate the role of RUNX1 mutations to the myeloid transformation in ASXL1-mutated leukemia, we performed in vitro and in vivo expressing either ASXL1 or RUNX1 single mutant or combination of ASXL1 with RUNX1 mutant." (PMID 31640815, 2019). "Coexpression of ASXL1-MT and BAP1 promoted RUNX1-ETO9a-induced leukemia progression with higher efficiencies than did ASXL1-MT alone." (PMID 30013160, 2018). "We demonstrate that CDK6 has pRB-independent role in adipogenesis by regulating RUNX1, one of the downstream effectors of CDK610 known to be frequently mutated in human leukemia and play a role in hematopoiesis." (PMID 29523786, 2018). "We then assessed the effect of coexpression of BAP1 and ASXL1-MT on the leukaemogenicity of RUNX1-ETO leukemia." (PMID 30013160, 2018). "In contrast, chromosomal translocations involving RUNX1 are detectable in utero, suggesting an initiating role in leukemias." (PMID 29052866, 2018). "Our data demonstrate that RUNX1/ETO maintains leukemia by promoting cell cycle progression and identifies G1 CCND-CDK complexes as promising therapeutic targets for treatment of RUNX1/ETO-driven AML." (PMID 30300583, 2018). "Runx1 has been most intensively studied in the hematopoietic system because its function is frequently corrupted in different subtypes of leukemia." (PMID 29030345, 2018). "Our findings represent the first characterization of this CASC15 in RUNX1-translocated leukemia, and point towards a mechanistic basis for its action." (PMID 28724437, 2017). "Relapsed childhood ETV6/RUNX1-positive leukemia is a clinically and biologically heterogeneous disease." (PMID 28418909, 2017). "It has been well documented that translocations of Runx1, the essential hematopoiesis factor, with ETO, TEL (ETV6) or other genes cause a wide range of leukemias." (PMID 28407681, 2017). "Of note, mutations in several of the genes that confer leukemia predisposition (e.g., CEBPA, ETV6, GATA2, NF1, RUNX1, PTPN11, CBL, and RAS) are also frequently found in sporadic acute myeloid leukemia (AML) or myelodysplastic syndrome (MDS)." (PMID 29326930, 2017). "Overexpression of miR-17,by reducing RUNX1 level, can mimic the single cell effects of the RM8 leukemia genetic mutation." (PMID 29156756, 2017). "RUNX1 plays fundamental roles in definitive hematopoiesis, and genetic aberrations of RUNX1 gene are involved in the pathogenesis of leukemia." (PMID 29050333, 2017). "Here, we assess the roles of the lncRNA CASC15 in regulation of a chromosomally nearby gene, SOX4, and its function in RUNX1/AML translocated leukemia." (PMID 28724437, 2017). "Accordingly, differentiation of RUNX1/ETO cells is blocked at an early myeloid stage and about 40% of the immature M2-type of leukemia are RUNX1/ETO dependent." (PMID 26990877, 2016). "Several studies on leukemia have already shown that cell context and cellular dosage are relevant for RUNX1 activity." (PMID 26735887, 2016). "Although the mechanism of RUNX1 activity is currently not understood, these results demonstrate a genetic requirement for Runx1 for efficient CBFβ-SMMHC induced leukemia in mice." (PMID 27542261, 2016).
leukemia (continued). "Loss of BCL2 modifying factor (BMF), a proapoptotic member of the BCL2 family, was recently shown in a single nucleotide polymorphism (SNP) array study to play a role in the development and relapse of ETV6/RUNX1 positive leukemia." (PMID 26919255, 2016). "At the molecular level there is evidence of a dynamic balance of RUNX1 and RUNX1/ETO activity in leukemia cells." (PMID 26990877, 2016). "ChREBP promoted leukemia cell differentiation through the direct inhibition of RUNX1 or the transactivation of TXNIP to downregulate the RUNX1 level and ROS generation." (PMID 27224916, 2016). "First, we used primary leukemia patient samples to identify an ETV6/RUNX1 specific expression signature consisting of 596 lncRNA transcripts." (PMID 27650541, 2016). "Deregulated expression of BCL2 family members has been described in the context of ETV6/RUNX1 positive leukemia." (PMID 26919255, 2016). "Extensive studies of RUNX1 had been conducted in leukemia and haematopoiesis, and RUNX1 was recognized as a suppressor for leukemogenesis." (PMID 26716895, 2016). "Increasingly it is becoming apparent that, in addition to a more classically defined tumor suppressor role, WT RUNX1 is required for the promotion of leukemogenesis in certain leukemia subtypes." (PMID 26808730, 2016). "While this is the most common chromosomal alteration to the RUNX1 gene, up to ten other translocations have been found to disrupt this gene in leukemia." (PMID 26483790, 2015). "Mitani found that RUNX1-related chimeras generated by the chromosomal translocations repress transcriptional activity of wild-type RUNX1 (AML1) by recruiting the co-repressor/histone deacetylase complex in leukemia cell lines." (PMID 26674644, 2015). "The decreased expression of miR-181a-1 in ETV6/RUNX1-positive leukemias was validated in another cohort of pre-B ALL cases analyzed by real-time qRT-PCR." (PMID 26580398, 2015). "We propose VPA to be an attractive choice in the molecular targeting therapy of RUNX1-Evi-1-related leukemia." (PMID 26674644, 2015). "Among these, we focused on miR-17-5p (hereafter simply referred to as miR-17), a miRNA that targets RUNX1-3′UTR, plays a key role in RUNX1-mediated control of myeloid differentiation, and is often upregulated in leukemia." (PMID 25612891, 2015). "The cells originating from the PML/RARα-, RUNX1/RUNX1T1- or DEK/NUP214-positive LT-HSCs induced leukemia with a high penetrance of 70%, 50% or 80%, respectively." (PMID 25568664, 2014). "In the first class, oncogenes (RUNX1, FLT3, LEF1) or tumor suppressors (RUNX1, CEBPA) implicated in leukemia were selected." (PMID 24786086, 2014). "The importance of RUNX1 function in hematopoiesis and leukemia has generated great interest in determining the factors that regulate its expression." (PMID 24904756, 2014). "Translocations of RUNX1 are seen in several types of leukemia with at least 21 identified partner genes." (PMID 24646765, 2014). "Only a truncated form and the “short” RUNX1/RUNX1T1ex9 isoform allowed an efficient leukemia induction in a transduction/transplantation model." (PMID 25568664, 2014). "STAT activation can also be regulated by the phosphatase activity of CD45 as shown for RUNX1/RUNX1T1-positive leukemia." (PMID 25568664, 2014). "Overall, hippuristanol demonstrated the most potent and consistent inhibition of the IRES-containing transcripts (LEF1, RUNX1) in two different leukaemia cell lines." (PMID 25392452, 2014). "To identify the cell population that maintains the PML/RARα- or RUNX1/RUNX1T1-positive leukemias, we transferred 2×104 cells from leukemic mice, with a tumor load of at least 80%, into sublethally irradiated secondary recipient mice." (PMID 25568664, 2014). "It is interesting that DS-AMKL leukemias contain three copies of the RUNX1 gene (owing to trisomy 21), as well as having a remarkably high frequency of cohesin mutation (53%)." (PMID 24904756, 2014).